Y_RNA (Y RNA )
Gene: Miscellaneous RNA gene on chromosome X (10,061,222 to 10,061,323, forward strand). Ensembl gene ENSG00000202469.
Homologues: Orthologues: chimpanzee Y_RNA (100% identical), macaque Y_RNA (95% identical). Paralogues in human: RNY3 (93% identical), RNY3P1 (91% identical), Y_RNA (91% identical), Y_RNA (90% identical), Y_RNA (89% identical), Y_RNA (88% identical), RNY3P14 (87% identical), Y_RNA (87% identical), Y_RNA (86% identical), RNY3P11 (85% identical), RNY3P16 (85% identical), Y_RNA (85% identical), and 95 more.